KRAS (KRas proto-oncogene, GTPase)
Diseases named in the same sentence as KRAS in open-access papers (continued):
Sharing a sentence is not in itself a finding about the gene and the disease.
colorectal cancer (continued). "Unfortunately, before these differential responses to therapy were realized, thousands of colorectal cancer patients with KRAS exon 2 and other clinically significant RAS mutations had been treated with an agent that is now known to provide them no benefit." (PMID 26136684, 2015). "Activating mutations in the Kirsten rat sarcoma viral oncogene homolog (KRAS) loci are largely predictive of resistance to epidermal growth factor receptor (EGFR) therapy in colorectal cancer (CRC)." (PMID 25823645, 2015). "KRAS mutations are detected and investigated primarily in colorectal cancer, pancreatic cancer, and lung cancer." (PMID 26197069, 2015). "As KRAS mutations occur in approximately 40% of colorectal cancers, various drugs targeting downstream of RAS in the mitogen-activated protein kinase (MAPK) pathway have been evaluated as potential therapies." (PMID 26136684, 2015). "Increased synergistic activity of the drug combination was identified in colorectal cancer cell lines with concomitant KRAS and PIK3CA mutations." (PMID 26136684, 2015). "RALA activity was also detectable in HT29 colorectal cancer cells, which are KRAS wild-type and carry a BRAF V600E mutation." (PMID 26033452, 2015). "The aim of this study was to evaluate the prognostic role of MMR status, BRAF mutations and specific KRAS point mutation in 762 patients in Chinese population, and several clinicopathologic features to better stratify colorectal cancer patients." (PMID 25929517, 2015). "This is largely because KRAS mutation is not only linked to conventional adenomas but also associated with serrated adenomas in the development of colorectal cancer." (PMID 26042813, 2015). "In order to compare two PCR based mutation detection methods, a total of 99 colorectal cancer samples were tested for KRAS and/or BRAF status by castPCR and Therascreen." (PMID 25568935, 2015). "Mutations in the KRAS gene occur in multiple tumour types including colorectal carcinoma, non-small cell lung cancer and pancreatic carcinoma." (PMID 26101870, 2015). "Frequent overlap of BRAF P-loop mutations with KRAS mutations has been previously reported in colorectal carcinomas." (PMID 26506417, 2015). "When HCT116 colorectal carcinoma cells, which express KRas with a G13D mutation, were intoxicated with PA in combination with LFNDUF5Vv or LFNDUF5Ah, significant cell morphological changes were observed and Ras was undetectable by western blotting." (PMID 26051945, 2015). "Primary samples from 762 colorectal carcinoma patients were analyzed for KRAS, BRAF gene mutations and MMR status." (PMID 25929517, 2015). "Until recently, indications for standard-of-care molecular testing in colorectal carcinomas included testing for KRAS mutational status as a predictor of response to anti–epidermal growth factor receptor (EGFR) agents such as cetuximab." (PMID 26366557, 2015). "The aim of our study was to evaluate the pathological and molecular features of specific KRAS mutated colorectal carcinomas." (PMID 25929517, 2015). "Some mutations in the KRAS gene (approximately 40% of colorectal carcinomas) and the NRAS gene (approximately 1%–6%) are associated with poor prognosis and a lack of response to anti-EGFR antibody therapy such as cetuximab and panitumumab." (PMID 26101870, 2015). "In colorectal cancer, different mutations in KRAS (exon 12 and 13), associated with resistance to EGFR monoclonal antibody therapy, were found in the same patient." (PMID 25222836, 2014). "KRAS mutations are frequently found in colorectal cancer (CRC) indicating the importance of its genotyping in the study of the molecular mechanisms behind this disease." (PMID 24720724, 2014). "Among the most important members of the family is KRAS, which is mutated in over 30% of colorectal cancers and predicts poor response to anti-EGFR therapy." (PMID 24874471, 2014).
colorectal cancer (continued). "As current clinical practices in colorectal cancer revolve around KRAS, NRAS, and BRAF mutation status, diagnostic sequencing of either primary or metastatic tissue as available is acceptable for most patients." (PMID 25164765, 2014). "These include BRAF V600 mutation for melanoma, EGFR mutation and ALK fusion for lung cancer, HER2 amplification or overexpression for breast cancer, and KRAS mutation for colorectal cancer." (PMID 25593991, 2014). "We also performed a comprehensive review on KRAS codon 61 and 146 mutations in colorectal cancer, and our curated literature data can be readily useful for public databases such as the COSMIC (Catalogue of Somatic Mutations in Cancer) database." (PMID 24885062, 2014). "The results shown here are reminiscent of the tumor evolution model proposed by Fearon & Vogelstein for colorectal cancer in which KRAS mutations were a later change in the tumor." (PMID 24742923, 2014). "KRAS being the most frequently mutated in human cancers with ~30% in colorectal cancers are the hallmarks in all these tumor samples." (PMID 24943349, 2014). "Clinical pathological and immunohistochemical findings in colorectal cancer cases with novel KRAS mutations." (PMID 25412182, 2014). "KRAS mutation analysis is commonly performed on tissue samples obtained from primary colorectal cancers (CRCs)." (PMID 25202344, 2014). "Clinical and metabolic parameters of the 108 non-small cell lung cancer (NSCLC) and 116 colorectal cancer (CRC) patients screened for KRAS mutations." (PMID 25158139, 2014). "In colorectal cancer they coexist with KRAS mutations and are considered to be co-responsible for the resistance to targeted therapy." (PMID 24932282, 2014). "Activated KRAS signaling is associated with multiple cancer types, including colorectal cancer (CRC), non-small cell lung cancer (NSCLC) and pancreatic ductal adenocarcinoma (PDAC)." (PMID 25245095, 2014). "Mutations in SMAD4 have been reported to frequently co-exist with KRAS mutations in colorectal cancer, and studies in pancreatic cancer suggest that wildtype SMAD4 blocks progression of KRAS G12D-initiated tumors." (PMID 25523272, 2014). "Approximately 40% of colorectal cancers harbors a mutation in the KRAS gene causing this pathway to be constitutively active." (PMID 25401499, 2014). "In colorectal cancers, KRAS mutations are known to determine the clinical efficacy and acquired resistance to EGFR targeting." (PMID 24970817, 2014). "In summary, our study reports that the incidence of KRAS mutation in Albanian colorectal cancer patients is less frequent when compared with the data from literature (35-50%)." (PMID 25267307, 2014). "Clinical and metabolic parameters in non-small cell lung carcinoma (NSCLC) and colorectal cancer (CRC) patients with the same KRAS mutational status." (PMID 25158139, 2014). "This is significant because many cancers of endodermal origin such as pancreatic, lung and colorectal cancer are strongly associated with KRAS mutations." (PMID 25109951, 2014). "The incidence of KRAS mutations has been found in 80% of advanced pancreatic cancer, 45% of cholangiocarcinoma and 32% of colorectal cancer patients." (PMID 25120700, 2014). "One of the most important amplified genes is the proto-oncogene KRAS, a small GTPase that is frequently mutated in lung, pancreatic and colorectal cancers." (PMID 24874471, 2014). "Several studies have addressed the prognostic-predictive value of KRAS mutational status in colorectal cancer patients." (PMID 25491325, 2014). "For these reasons, the SW620 human colorectal cancer cell line, which contains an activating KRAS (G12V) mutation, was used in the present study." (PMID 25427200, 2014). "Tumors with KRAS mutations in codons 61 and 146 account for an appreciable proportion (approximately 5%) of colorectal cancers, and their clinicopathological and molecular features appear generally similar to KRAS codon 12 or 13 mutated cancers." (PMID 24885062, 2014).
colorectal cancer (continued). "Multiple genetic alterations were reported to be more common in younger patients with papillary thyroid cancer, while younger patients with colorectal cancer showed a high frequency of KRAS mutations." (PMID 25348872, 2014). "Overall, our results seem to confirm that KRAS mutations are associated with a more aggressive form of colorectal cancer." (PMID 25491325, 2014). "The human colorectal cancer cell line DiFi, which harbors wild-type alleles of KRAS, BRAF, and PI3K, is highly sensitive to cetuximab." (PMID 25474137, 2014). "In one Phase I study, colorectal cancer patients underwent prospective molecular profiling for mutations in KRAS, BRAF, PIK3CA and expression levels of PTEN and pMET." (PMID 25401499, 2014). "In order to analyze the survival rate of the patients with colorectal cancer we only focused on the status of KRAS mutation." (PMID 25713627, 2014). "Research primarily in colorectal cancer shows that KRAS mutations occur most commonly in codons 12 and 13, usually precede the development of malignancy, and are maintained in secondary disease sites." (PMID 25491325, 2014). "Several mutational landmarks have been described in the progression to colorectal cancer, such as KRAS, BRAF and PI3K mutations, and were analyzed in our samples." (PMID 24516561, 2014). "Clinical and metabolic parameters in non-small cell lung carcinoma (NSCLC) and colorectal cancer (CRC) patients with transition or transversion mutations in KRAS." (PMID 25158139, 2014). "Several studies on colorectal cancer (CRC) have shown that KRAS gene mutations impair response to the drug." (PMID 24642661, 2014). "The expression of miR-126 and its host gene is reduced in most cancers including those with a high frequency of KRAS mutations such as colorectal cancer, lung cancer and pancreatic ductal carcinoma." (PMID 25245095, 2014). "Since our patients had only received standard chemotherapy and none of them had targeted medicine after resection, our findings support KRAS codon 13 (G13D) mutation as a prognostic biomarker in the natural process of colorectal cancer." (PMID 25367198, 2014). "Because KRAS mutation frequently occurs in colorectal cancer patients, it is important to explore efficient therapies for patients harboring a KRAS mutation." (PMID 25427200, 2014). "It is of interest to examine the characteristics of colorectal cancers with KRAS mutations in codons 61 and 146, compared to those in codons 12 and 13, and KRAS-wild-type cases." (PMID 24885062, 2014). "The KRAS oncogene is mutated in approximately 35%-45% of colorectal cancers, and KRAS mutational status testing has been highlighted in recent years." (PMID 25713627, 2014). "Mutations in KRAS can be identified in 30-40% of colorectal cancers and mutated KRAS is constitutively active independent of EGFR signaling." (PMID 25551625, 2014). "For this reason, routine screening of colorectal cancer patients for KRAS mutations is now carried out." (PMID 25109951, 2014). "The mutation occurred in isolation in only 2/17 (12%) patients, and KRAS was frequently found as a concomitant mutation, especially in patients with colorectal cancer (6/7; 86%)." (PMID 24586741, 2014). "Acquired KRAS mutations have also been implicated as a mechanism of resistance after anti-EGFR targeted therapy in colorectal cancer." (PMID 25119929, 2014). "The specific KRAS mutations in colorectal cancer were similar to those previously reported in a smaller series, in which G12D and G12V were the two most commonly seen mutations." (PMID 25313136, 2014). "Methylation levels were correlated with MSI and CIMP statuses and known mutations within the APC, BRAF and KRAS genes in 264 matched samples representing the progression from normal to pre-invasive adenoma to colorectal carcinoma." (PMID 25432628, 2014). "There are seven point mutations in codon 12 and 13 that together account for approximately 95% of all KRAS mutations in colorectal cancer." (PMID 24280411, 2013).
colorectal cancer (continued). "A total of 47 colorectal cancer patients were confirmed to carry KRAS mutation by COLD-PCR/Sanger sequencing." (PMID 23874486, 2013). "In colorectal cancer, KRAS and BRAF mutations have been shown to identify a cluster of patients that does not respond to anti-EGFR therapies; the identification of these mutations is therefore clinically extremely important." (PMID 23536897, 2013). "Recently, for KRAS mutation analysis in colorectal cancer, arbitrary thresholds for correct KRAS mutation identification was set at 97%." (PMID 23935912, 2013). "Conversely, coexisting KRAS mutations confer the resistance of PIK3CA mutant colorectal cancer to PI3K/mTOR inhibitors in preclinical and in clinic studies." (PMID 23826249, 2013). "The mutation status of the BRAF and KRAS genes has been proposed as prognostic biomarker in colorectal cancer." (PMID 24073892, 2013). "Examples in treatment of solid tumors include ERBB2 (HER2) gene amplification in breast and gastric cancer, EGFR mutation in non-small cell lung cancer, and KRAS mutation in colorectal cancer." (PMID 23700467, 2013). "Based on data in the literature, multiple mutations in the KRAS gene are infrequent, representing 2.1% of mutations in colorectal cancer." (PMID 23761841, 2013). "First, regarding KRAS mutation, the efficacy of cetuximab is associated with longer overall and progression-free survival among patients with chemotherapy-refractory colorectal cancer with p.G13D-mutated tumors than with other KRAS-mutated tumors." (PMID 23824671, 2013). "An analysis of the results indicated different clinical features and outcomes between the colorectal cancer patients with wild-type and mutated KRAS." (PMID 29147353, 2013). "KRAS A146T mutations have been seen in both colorectal cancers and colonic adenomas, and were associated with a more favorable outcome." (PMID 24066160, 2013). "For example, the RASCAL cooperative was for all stages of colorectal cancer and 12 possible mutations on codons 12 and 13 of KRAS were assessed." (PMID 23930204, 2013). "Evaluation of the KRAS mutational status is a crucial step for the correct therapeutic approach in advanced colorectal cancer." (PMID 23761841, 2013). "Clinical studies shows that the KRAS codon 12 mutation, especially the c.35G>T (p.G12V) mutation, was associated with the highest colorectal cancer–specific mortality." (PMID 23437064, 2013). "Both MEK/ERK and GSK3 signaling pathways are thought to be affected in early stages of colorectal cancer formation due to frequent mutations in KRAS/BRAF and APC genes respectively." (PMID 23919615, 2013). "Evaluation of the mutational status of KRAS is a crucial step for the correct therapeutic approach in treating advanced colorectal cancer as the identification of wild-type KRAS tumors leads to more specific and less toxic treatments for patients." (PMID 23761841, 2013). "Nevertheless, in the context of KRAS, the vast majority of mutations occur on amino acids 12, 13 and 61 for both lung and colorectal cancer." (PMID 23758891, 2013). "In summary, we have found that PIK3CA mutation in colorectal carcinomas correlated with tumor proximal colonic location, mucinous differentiation, KRAS mutation, high levels CIMP and loss of MGMT expression." (PMID 23785428, 2013). "Other studies have shown that colorectal carcinomas with KRAS mutation display mucinous differentiation more frequently than carcinomas with wild-type KRAS." (PMID 23785428, 2013). "BRAF and KRAS mutational analysis of lung adenocarcinoma, malignant melanoma and colorectal carcinoma by NGS LA: lung adenocarcinoma; MM: malignant melanoma; CRC: colorectal cancer." (PMID 23922754, 2013).
colorectal cancer (continued). "In this model, point mutations in KRAS were described as an early event in the pathogenesis of colorectal cancer." (PMID 23202889, 2012). "RASCAL II confirmed that a glycine to valine mutation on codon 12 of the KRAS gene has a significant association with biological behavior of colorectal cancer." (PMID 23202889, 2012). "As shown with this review, KRAS mutations have a significant impact on colorectal cancer and the treatment strategies against it." (PMID 23202889, 2012). "It has been reported that the use of cetuximab was associated with longer overall and progression-free survival among patients with chemotherapy-refractory colorectal cancer with G13D-mutated tumors than patients with other KRAS-mutated tumors." (PMID 22586484, 2012). "In colorectal cancer cell lines, there was strong expression of Abi1 in lysates from KRAS-mutated cells, but only a very faint signal in lysate from BRAF-mutated cells." (PMID 22808230, 2012). "The oncogene KRAS belongs to the protein family of small G-proteins and is mutated in 35-40% of colorectal cancers (CRC)." (PMID 22876876, 2012). "Twenty formalin-fixed paraffin-embedded human colorectal cancer samples from colon resections previously tested for KRAS mutations were selected based on mutation status (6 wild type, 8 codon 12 mutations, and 6 codon 13 mutations)." (PMID 22534075, 2012). "In 238 patients with colorectal cancer referred to our clinical trials unit, we found that 122(51%) had KRAS mutations." (PMID 22675430, 2012). "In terms of therapy KRAS mutational status has been linked to EGFR inhibitor resistance in colorectal cancer, but further studies are needed in endometrial carcinoma to explore such potential link." (PMID 23300780, 2012). "Like let-7 miRNA, miR-143 has been implicated in colorectal cancer as a link to KRAS-driven carcinogenesis and is shown to bind to the 3′-UTR of the KRAS gene." (PMID 23202889, 2012). "For patients with advanced colorectal cancer, the testing of mutation status of oncogenes such as KRAS is required for guiding therapy." (PMID 22675560, 2012). "For instance, mutations in KRAS are effective predictors of colorectal cancer patients’ responses to cetuximab, and mutations in PIK3CA are correlated with resistance to cetuximab treatment in colon cancer cell lines." (PMID 22994622, 2012). "A recent study showed that KRAS mutations result in resistance to cetuximab in colorectal cancer, limiting the utility of this drug." (PMID 22994622, 2012). "In fact, KRAS mutations were demonstrated in 50% of adenomas and described as a key genetic alteration necessary for the progression of adenoma to colorectal cancer." (PMID 23202889, 2012). "KRAS mutations are observed in approximately 45-60% of pancreatic cancers, 30-50% of colorectal cancers and 30% of non-small-cell lung carcinomas." (PMID 22994622, 2012). "Univariate and multivariate logistic regression model for clinical characteristics associated with KRAS mutations in colorectal cancer." (PMID 22675430, 2012). "KRAS mutations are also observed in 40 – 50% of colorectal cancers and 10 - 30% of Non-Small Cell Lung Cancers (NSCLCs)." (PMID 22995035, 2012). "The most frequent mutations observed in colorectal cancer patients are found at codons 12 and 13 of KRAS, in approximately 35% of the patients, and the V600E mutation of BRAF, found in about 15% of the cases." (PMID 23207070, 2012). "We evaluated the association between a KRAS mutational status and various clinicopathologic features including the metastatic pattern in patients with metastatic or recurrent colorectal cancer (MRCRC)." (PMID 22876814, 2012). "We investigated the effectiveness of peptide nucleic acid (PNA) clamp PCR for detecting KRAS mutations in peripheral blood samples of colorectal cancer (CRC) patients." (PMID 23226727, 2012). "No significant response to therapy with anti-EGFR antibodies have been observed in colorectal cancer patients exhibiting KRAS mutations." (PMID 22931052, 2012).